NEK8 (NIMA related kinase 8)
Diseases named in the same sentence as NEK8 in open-access papers (continued):
Sharing a sentence is not in itself a finding about the gene and the disease.
chronic kidney disease (1 paper, 2023). Impairment of the renal function secondary to chronic kidney damage persisting for three or more months. "The other interesting alternatively spliced genes were engaged in chemical carcinogenesis (ARAF), chronic kidney disease (NEK8) and kidney development (CNTRL, TET2, NLE1)." (PMID 38074096, 2023).
colon cancer (1 paper, 2023). "We discovered new colon cancer related genes including AC007952.4, NEK8, CHRM3, ANO7, B3GNT6, NEURL1, ODC1 and KCNMA1." (PMID 36944972, 2023).
colorectal tumor (1 paper, 2023). "Collectively, these findings suggest that c-MYC S405 phosphorylation is essential for NEK8-mediated colorectal tumor progression." (PMID 37596667, 2023).
hepatocellular carcinoma (1 paper, 2017). A malignant tumor that arises from hepatocytes. "The retrocopy can fold into a hairpin structure due to inverted repeats and can be processed in at least two endo-siRNAs, one of which downregulates the parental gene and NIMA-related Kinase 8 (NEK8) gene, inhibiting cell proliferation in hepatocellular carcinoma." (PMID 28406439, 2017).
Hydroureter (1 paper, 2016). The distention of the ureter with urine. "In contrast, Nek8 knockout mice (Nek8tm1Bei) present a mild renal phenotype, with dilated proximal tubules and glomerular cysts and the mouse model with a missense mutation (p.I124Y) in the kinase domain (Nek8roc) exhibits hydroureter, cystic tubular dilations and small glomerular cysts." (PMID 26967905, 2016).
influenza infection (1 paper, 2013). "The majority of the hits were novel; however, PANK4, NEK8, ITPKB, CALM2 and HK2 have been identified in other influenza screens." (PMID 23805279, 2013). "In addition, four of the six (HK2, NEK8, PANK4, PLK4) have also been identified important for influenza virus replication in other influenza-genome screens." (PMID 23805279, 2013).
Insulin resistance (1 paper, 2022). Increased resistance towards insulin, that is, diminished effectiveness of insulin in reducing blood glucose levels. "The in vivo role of NEK8 was explored in a mouse model of high-fat diet- (HFD-) induced insulin resistance." (PMID 36506932, 2022). "Functionally, lentiviral-mediated NEK8 inhibition ameliorates HFD-induced insulin resistance in adipocytes." (PMID 36506932, 2022).
invasive ductal breast carcinoma (1 paper, 2023). The most common type of invasive breast carcinoma, accounting for approximately 70% of breast carcinomas. "NEK8 mRNA expression was 1.495-fold higher in invasive ductal breast carcinoma samples than in normal tissues (P = 8.43e−8)." (PMID 37100815, 2023).
liver fibrosis (1 paper, 2025). "Pathogenic variants in IFT88, which are related to Bardet-Biedl Syndrome, can lead to liver fibrosis, while ALMS1 (linked to Alström Syndrome) and NEK8 (associated with Nephronophthisis) are involved in renal cysts and liver fibrosis." (PMID 40277920, 2025).
pancreatic cancer (1 paper, 2021). "For example, missense mutations in NEK8 are underlying driver mutations in pancreatic cancer." (PMID 34374193, 2021). "NEK8 is overexpressed in breast and pancreatic cancer and affects prognosis." (PMID 34374193, 2021).
peritoneal cancer (1 paper, 2025). A peritoneum cancer that is located in the inside of the abdomen. "In summary, NEK8 facilitates GC progression and peritoneal cancer dissemination in vivo." (PMID 39762761, 2025). "Additionally, infected cells were injected into the abdominal cavities of nude mice to assess whether NEK8 regulates GC peritoneal cancer dissemination in vivo." (PMID 39762761, 2025).
renal dysplasia (1 paper, 2016). Renal dysplasia is a form of renal malformation in which the kidney(s) are present but their development is abnormal and incomplete. "Based on our results, NEK8 seems to be a major gene for renal dysplasia, since mutations were identified in 5 out of 200 analyzed families with dysplastic kidneys." (PMID 26967905, 2016).
situs inversus (1 paper, 2016). A congenital condition in which there is complete right-to-left reversal of the position of the major thoracic and abdominal organs (that is, they are arranged in a mirror image of the normal positioning). "Here, we describe 8 novel NEK8 mutations in five cases with severe multi-organ developmental defects, and the first association of NEK8 mutations with renal hypodysplasia and agenesis, situs inversus, agenesis of the vermis and bile duct paucity." (PMID 26967905, 2016).
cancer (14 papers, 2016 to 2025). A tumor composed of atypical neoplastic, often pleomorphic cells that invade other tissues. "Results showed that loss of NEK8 could significantly inhibit the proliferation ability of cancer cells in vivo." (PMID 37596667, 2023). "Therefore, NEK8 overexpression is likely to induce the phosphorylation of proteins involved in cancer progression, namely those associated with proliferation, invasion, metastasis, and drug resistance." (PMID 37100815, 2023). "Additionally, NEK8 has been identified as a tumor-associated gene that promotes cancer cell proliferation, colony formation, and migration." (PMID 36506932, 2022). "Indeed, several NEK proteins such as NEK2, NEK6, and NEK8 are overexpressed or mutated in various types of cancer." (PMID 27602754, 2016). "Other genes of interest among these 15 include Tusc3, a candidate tumor suppressor gene, and Nek8, which plays a role in cell cycle progression and has been reported to affect cancer progression." (PMID 40112176, 2025). "The roles of Nek8 in the cell are diverse, and include cilia regulation, processes deregulated in cancer, and DDR." (PMID 35409400, 2022). "We first analysed the pan‐cancer expression of NEK8 by using the combined data gathered from TCGA and GTEx." (PMID 34374193, 2021). "Another study showed an association between NEK8 and VHL in cancer cells." (PMID 32294979, 2020). "Further studies should be conducted to better understand the involvement of NEK8 in cancer." (PMID 32294979, 2020). "Besides, we found that silencing of c-MYC could abrogate NEK8-mediated increase in cancer cell proliferation, cellular ATP, and DNA replication." (PMID 37596667, 2023). "These two functions may explain the role of NEK8 in the occurrence and development of cancer." (PMID 34374193, 2021).
tumor (8 papers, 2021 to 2025). "The role of NEK8 overexpression on tumor progression was associated with its interactions with b-catenin in the Wnt/β-catenin pathway leading to increased cancer cell motility." (PMID 39975112, 2025). "Knocking down NEK8 was effective in reducing tumor proliferation but loss of NEK8 also reduced RAD51 localization, promoting HR deficiency." (PMID 39975112, 2025). "We determined Spearman correlation coefficients to analyse associations between NEK8 expression and immune cell infiltration via ssGSEA in the tumour microenvironment." (PMID 34374193, 2021). "At this point, the tumor xenograft experiments demonstrated that NEK8 overexpression accelerated GC proliferation and increased tumor volume in vivo." (PMID 39762761, 2025). "NOD/SCID mice inoculated with 104, 103, and 102 NEK8-knockdown cells exhibited a considerably lower incidence of tumour initiation than mice inoculated with shCtrl cells." (PMID 37100815, 2023). "Results showed that the growth rate and weight of tumors induced by c-MYC S405A cells were significantly lower than tumors induced by c-MYC WT cells, and the c-MYC S405A mutant abrogated the NEK8-mediated increase in tumor proliferation ability." (PMID 37596667, 2023). "The tumours were stained with NEK8 antibodies and the expression of NEK8 was found to be lower in the shNEK8 group than in the shCtrl group." (PMID 37100815, 2023). "The TNMplot data revealed that NEK8 mRNA expression was higher in tumours than in normal tissues (P = 4.76e−20)." (PMID 37100815, 2023). "Regarding stem-cell characteristics, NEK8 knockdown decreased the tumour sphere formation, aldehyde dehydrogenase activity, and stem-cell marker expression, including that of CD44, Sox2, Oct4a, and Nanog." (PMID 37100815, 2023). "A functional enrichment analysis of TCGA data further showed that the high NEK8 expression group was enriched for terms related to development and morphogenesis of organs, tissues, proliferation, differentiation and the tumour microenvironment." (PMID 34374193, 2021). "The connection between NEK8 and tumor biology was first described in breast cancer." (PMID 39762761, 2025). "The results indicated that high NEK8 levels predominantly impact tumor metabolism pathways." (PMID 39762761, 2025). "Additionally, according to the UALCAN database, the mRNA expression levels of NEK2, NEK3, NEK4, NEK5, NEK6, and NEK8 were significantly positively correlated with the tumour grade, whereas that of NEK10 was inversely associated with this factor." (PMID 38706902, 2024). "Next, we further investigated the detailed mechanism of NEK8-mediated tumor proliferation." (PMID 37596667, 2023). "Furthermore, the NEK8 knockdown via shRNA in MDA-MB-231 cells inhibited the tumour-initiating and metastatic potential of MDA-MB-231 cells in vivo." (PMID 37100815, 2023). "However, the detailed mechanism of NEK8-mediated tumor proliferation has been largely understudied." (PMID 37596667, 2023). "Also, NEK8 knockdown significantly reduced tumour volume and weight." (PMID 37100815, 2023). "NEK8-silenced MDA-MB-231 cells inhibited xenograft tumour growth, metastasis, and tumour initiation in vivo." (PMID 37100815, 2023). "We then performed quantitative PCR using our clinical tissue samples and found that the mRNA levels of NEK8 were higher in both grade III and grade IV samples than in non‐tumour specimens." (PMID 34374193, 2021). "Although there have been several studies about the biological function of NEK8, most were about non-neoplastic disease, and the role of NEK8 in tumorigenesis and tumor progression remains unclear." (PMID 37596667, 2023).
kidney disease (3 papers, 2021 to 2025). "Interestingly, it was shown that Nek8 interacts with TAZ, linking Nek8 and kidney disease to the TAZ/Hippo signaling pathway, and potentially linking Nek8 to tumourigenesis." (PMID 35409400, 2022).
infection (1 paper, 2013). The state of being infected such as from the introduction of a foreign agent such as serum, vaccine, antigenic substance or organism. "Though NEK8 transcript is significantly induced by 24 hrs post A/WSN/33 infection." (PMID 23805279, 2013). "Of the 17 HPK genes identified important for A/WSN/33 replication, six (CDK13, HK2, NEK8, PANK4, PLK4, SGK3) emulated the phenotype following A/New Caledonia/20/99 infection, i.e. increased or decreased virus replication as measured by influenza NP localization and influenza M gene levels." (PMID 23805279, 2013).
NEK8 also shares sentences with these, for which no sentence is quoted: Obesity (2 papers); autosomal dominant polycystic kidney disease (1); Charcot-Marie-Tooth disease (1); Diarrhea (1); focal segmental glomerulosclerosis (1); Fundus dystrophy (1); hearing loss (1); Immunodeficiency (1); Joubert syndrome (1); metabolic disorders (1); nemaline myopathy (1); nephrotic syndrome (1); non-syndromic intellectual disability (1); oligodendroglioma (1); osteosarcoma (1); ovarian carcinoma (1); Periportal fibrosis (1); prostate carcinoma (1); renal cell carcinoma (1); Renal insufficiency (1); rheumatoid arthritis (1); Rod-cone dystrophy (1); Seckel syndrome (1); stomach cancer (1); thrombotic microangiopathy (1); type 2 diabetes mellitus (1); uveal melanoma (1).